CP (ceruloplasmin)
Diseases named in the same sentence as CP in open-access papers (continued):
Sharing a sentence is not in itself a finding about the gene and the disease.
lung carcinoma (continued). "More importantly, higher levels of CP were significantly correlated with a shorter relapse free survival and overall survival in lung cancer patients from the KM-Plotter and GEPIA databases." (PMID 32708433, 2020). "Consistently, a restoring role of miR-145-5p was found in all consequences caused by CP dysregulation, including imbalance of Fe2+, PHD1/2 inactivation, then increased HIF-2α levels in lung cancer cells, even in normoxic microenvironments." (PMID 32708433, 2020). "Further studies are needed to more precisely evaluate disturbances in circulating Cu in lung cancer, mainly via assessment of the relative levels of free- and ceruloplasmin-bound Cu and their influence on cancerogenesis and mortality." (PMID 33375477, 2020). "HIF-2α has been previously shown to control various cancer behaviors; the following experiments were performed to determine the pathologic roles of CP in lung cancer." (PMID 32708433, 2020). "Taken together, our study suggests that ceruloplasmin, lipocalin 2 and periostin are potential candidate biomarkers at early stages for lung cancer." (PMID 28088789, 2017). "By contrast, we found that CP levels were markedly elevated in the urine of lung cancer patients from the same cohort of patients and healthy controls." (PMID 26133466, 2015). "Using the doxycycline-inducible mutant Kras mouse model of lung cancer, we showed that urine ceruloplasmin (CP) levels increased as tumors progressed and decreased as tumors regressed." (PMID 26133466, 2015). "Western blotting revealed a slight increase in serum CP levels in the lung cancer patients, although this difference was not statistically significant." (PMID 26133466, 2015). "The most likely explanation of the present results thus is that high serum ceruloplasmin levels in lung cancer are mainly due to occult cancer." (PMID 1739632, 1992). "Moreover, high expression of CP in tumor cells, such as lung cancer, liver cancer, melanoma, and breast cancer, can inhibit ferroptosis, thus reduces tumor cell death and promotes tumor progression." (PMID 37637428, 2023). "Although CP is associated with tumor growth, invasiveness and prognosis in lung cancer patients, its biological role in tumorigenesis remains not fully understood." (PMID 35174082, 2022). "The ongoing oxidative and inflammatory disturbances in our cohort may also be demonstrated by the generally lower concentrations of albumin and higher CRP and ceruloplasmin concentrations in lung cancer patients compared to the control group." (PMID 34832849, 2021). "The aim of this study is to provide the relationship among HIFs, CP, iron and lung cancer." (PMID 32708433, 2020). "The regulatory loop of miR-145-5p and CP confirms that miR-145-5p and CP might be predictive biomarkers or promising strategies for lung cancer treatment." (PMID 32708433, 2020). "In addition, the 7 datasets identified from the Oncomine® database also showed that the levels of CP expression were increased in lung cancer tissue samples compared with normal tissue samples." (PMID 32708433, 2020). "It has been reported that ceruloplasmin levels were increased in sera of patients with various acute inflammatory conditions, including injury, malignancy, cardiovascular disease, infection, and adenocarcinoma lung cancer patients." (PMID 28088789, 2017). "Because the up-regulation of CP was identified in the urine of Kras mutation-positive lung cancer patients and in the mutant Kras-driven mouse model, we investigated whether CP could serve as a urine biomarker for lung cancer patients in general." (PMID 26133466, 2015). "CP has previously been reported to be increased in the serum of lung cancer patients." (PMID 26133466, 2015). "The same study also suggested that high serum CP levels in lung cancer may mainly be due to occult cancer." (PMID 26133466, 2015).
lung carcinoma (continued). "In addition, CP expression is increased in tumor cells of different tumors like liver cancer, lung cancer, and melanoma, thus transferring electrons to oxygen and oxidizing Fe2+ to Fe3+ via regulating copper, thereby reducing intracellular Fe2+ and inhibiting ferroptosis." (PMID 37637428, 2023). "In addition, levels of CP in tumor were correlated with lung cancer invasiveness and prognosis." (PMID 32708433, 2020). "Thus, we tested whether CP was up-regulated in the urine of lung cancer patients using rabbit anti-mouse and anti-human antibodies generated against CP." (PMID 26133466, 2015). "In contrast, inhibition of miR-145-5p by miRNA inhibitors increases the expression of CP and VEGF-A in lung cancer cells." (PMID 32708433, 2020). "Human normal bronchial epithelia (HBE) and lung cancer cell lines (CL1-0, CL1-5, H1299, H1563 and H1435) were used to test the expression of CP protein." (PMID 32708433, 2020). "Fucosylated alpha-1-acid glycoprotein (AGP), ceruloplasmin (CP), and paraoxonase 1 (PON1) in the serum may be potential biomarkers for lung cancer." (PMID 37256139, 2023). "We found that the expression of CP in CRC tissues was significantly lower than that in normal tissues, and these results are inconsistent with those reported for other cancers such as glioma and lung carcinoma." (PMID 35242040, 2022). "Our study shows that human lung cancer exhibits elevated levels of ceruloplasmin (CP), which has a negative impact on the prognosis of patients." (PMID 32708433, 2020). "However, the molecular mechanism by which CP contributes to lung cancer progression has not been well investigated." (PMID 32708433, 2020). "However, the detection of CP in the urine of lung cancer patients has not been reported." (PMID 26133466, 2015).
hepatocellular carcinoma (20 papers, 1997 to 2026). A malignant tumor that arises from hepatocytes. "The selected examples are diminished haptoglobin values in hepatocellular carcinoma, reduced hemopexin levels in prostate cancer patients, and downregulated ceruloplasmin in adrenocortical and hepatocellular carcinomas." (PMID 38201509, 2023). "In the same way, depletion of CP resulted in accumulation of ROS in astrocytes but also in hepatocellular carcinoma cells, thus in a tumor context." (PMID 35918659, 2022). "In contrast, the expression of most iron-regulatory genes, including ceruloplasmin, is significantly lower in the tumor tissues of patients with hepatocellular carcinoma than in their adjacent normal liver tissues." (PMID 34413268, 2021). "Several in vitro studies have confirmed its activity against hepatocellular carcinoma; however, in vivo studies of the effect of CP on liver cancer are needed." (PMID 34299510, 2021). "Despite previous research suggesting that copper supplementation cannot reverse CP-mediated ferroptosis in hepatocellular carcinoma cells 15, whether CP is involved in cuproptosis needs to be further explored." (PMID 38385087, 2024). "Both hypoxia and CuCl2 increased ceruloplasmin mRNA levels in hepatoma cells." (PMID 36520275, 2023). "Elevated copper and ceruloplasmin levels in serum and tumors, which are observed in hepatocellular carcinoma (HCC) 14, breast 15, lung 16, and hematological malignancies 17, are consistently associated with poor prognosis." (PMID 41355954, 2026). "CP prevents ferroptosis induced by erastin and RSL3 through regulating iron metabolism in hepatocellular carcinoma (HCC) cells." (PMID 35309911, 2022). "By contrast, the expression of ceruloplasmin is significantly downregulated in adrenocortical carcinoma (ACC) and hepatocellular carcinoma and correlated with a poor prognosis in ACC patients." (PMID 34413268, 2021). "The depletion of CP promotes erastin- and RSL3-induced ferroptotic cell death, whereas the overexpression of CP suppresses ferroptosis in hepatocellular carcinoma cells." (PMID 33117818, 2020). "In human hepatoma HepG2 cell line curdlan sulphate enhances basal and interleukin-6-stimulated fibrinogen and antichymotrypsin (ACT) synthesis, slightly increases basal ceruloplasmin production and exerts only minor effects on alpha-1-proteinase inhibitor and transferrin." (PMID 18472835, 1997). "For instance, in hepatocellular carcinoma (HCC), the increase in intracellular copper levels induced by ionizing radiation promotes the transcriptional activity of Hypoxia Inducible Factor 1 Subunit Alpha (HIF1A), thereby elevating the expression levels of ceruloplasmin and SLC7A11 within cells." (PMID 40200790, 2025).
Hepatitis (19 papers, 2005 to 2025). Inflammation of the liver. "We therefore recommend a three-step testing strategy for WND diagnosis for children younger than 8 years old: 1) liver function test (to exclude other causes of hepatitis, such as viral hepatitis etc.); 2) ceruloplasmin or urinary copper test; 3) genetic testing." (PMID 21219664, 2011). "Patients with hepatitis-mimic: low or normal ceruloplasmin; increased 24-h urinary copper excretion (>100 μg/24 h); increased non-ceruloplasmin-bound copper; and increased hepatic copper levels (>250 μg/g)." (PMID 40197188, 2025). "Hepatitis panel, ferritin, ceruloplasmin, alpha-1 antitrypsin, acetaminophen level, coagulation profile, lipid panel, glucose-6-phosphate dehydrogenase level, and autoimmune workup were within normal limits." (PMID 40308432, 2025). "In the hepatitis and control groups, CP, FIB-4, and NFS showed a strong positive correlation with GCA, as did APRI with TCA, TCDCA, and GCA." (PMID 39857662, 2024). "Hepatitis serologies for hepatitis B and C, ceruloplasmin, and autoimmune liver disease-related autoantibodies were negative." (PMID 37576148, 2023). "As expected, our study determined that F4/80 positive staining was enhanced in hepatitis and decreased after CP-25 administration." (PMID 36457713, 2022). "Although the levels of CP are downregulated in conditions like severe hepatitis, fulminant hepatitis and decompensated cirrhosis, the clinical significance of CP has not yet been clearly defined." (PMID 24282481, 2013). "In conditions of oxidative stress, restored CP activity may alleviate liver inflammation (hepatitis) and subsequent fibrosis, as well as neuroinflammation in WD patients." (PMID 41012571, 2025). "Thus, important labs to consider during workups include CBC, CMP, hepatitis panel, autoimmune panel, iron levels, and ceruloplasmin levels." (PMID 39493089, 2024). "Interestingly, patients with severe hepatitis were shown to have significantly lower levels of CP compared to patients with other liver diseases, except for WD." (PMID 24282481, 2013). "Although CP has been studied in conjunction with evaluating WD and severe hepatitis, to the best of our knowledge, this is the first study evaluating correlations between serum CP and fibrosis in CHB, and the first study to use CP as a noninvasive predictor of hepatic fibrosis and risk of cirrhosis." (PMID 24282481, 2013). "However, a significant correlation was shown between CP levels and inflammation, and an increase in the number of necrotic hepatic cells seen with moderate or severe liver inflammation (G3-4) resulted in an obvious reduction of CP." (PMID 24282481, 2013). "LFTs, hepatitis serologies, ANA, AMA, ASMA, Ferritin, Ceruloplasmin, and α1-AT, level were unremarkable." (PMID 24782928, 2014). "Serum hepatitis panel, ferritin, ceruloplasmin, alpha-1 antitrypsin, and autoimmune workup were within normal limits." (PMID 40308432, 2025). "Patient 6 had cholestatic jaundice, elevated liver enzymes, low serum ceruloplasmin, high urine copper, and a negative hepatitis profile noted in his medical records, but the exact figures were not available." (PMID 39559689, 2024). "The CP may also rise to the normal range in patients with WND who are pregnant, taking oral contraceptives, and suffering from infections and hepatitis." (PMID 37296680, 2023). "Hepatitis serologies, ANA, AMA, ASMA, Ferritin, Ceruloplasmin, and α1-AT, level were unremarkable." (PMID 24782928, 2014). "Although CP levels were previously shown to be decreased in patients with severe hepatitis, no studies to date have evaluated CP levels as a biomarker to predict fibrosis." (PMID 24282481, 2013). "The patient tests for hepatitis A, B, C, Epstein-Barrvirus (EBV), herpessimplex virus(HSV), cytomegalovirus(CMV) were negative and serum ceruloplasmin level and anti-liver-kidney microsomal antibody were in normal range; he had a negative history of taking medications or substance abuse." (PMID 34192168, 2020).
Hepatitis (continued). "Furthermore, recent Q-PCR measurements on non-copper related hepatitis and extra hepatic cholestasis suggest that ATP7A and CP are not down-regulated by inflammation or cholestasis (data not shown)." (PMID 15790412, 2005).
heart failure (15 papers, 2013 to 2025). Inability of the heart to pump blood at an adequate rate to meet tissue metabolic requirements. "Elevated levels of ceruloplasmin are associated with the general inflammation status of the body and help identify individuals at higher risk of developing heart failure or disease worsening." (PMID 35626917, 2022). "Previous studies have shown that increased levels of CP are associated with increased risk of developing heart failure." (PMID 36238639, 2022). "Recent studies indicate serum CP as an independent cardiac risk factor and show its association with heart failure." (PMID 24206753, 2013). "A meta-analysis identified a significant association between high serum copper and heart failure (HF), and the authors speculated that the association between HF and high ceruloplasmin concentrations was caused by high serum copper levels." (PMID 36520275, 2023). "Higher ceruloplasmin levels were associated with heart failure and were weakly associated with CVD." (PMID 35394150, 2022). "And in other studies, heart failure is associated with high levels of ceruloplasmin." (PMID 34948066, 2021). "The effects of NKG7 and CP expression on heart failure were less known, which required more attentions to illustrate the effects on cardiac remodeling and inflammation resolution." (PMID 40060963, 2025). "Serum levels of myeloperoxidase, vitamin D3, ceruloplasmin, and 8-hydroxy-2-0-deoxyguanosine correlate well with the stage of heart failure." (PMID 35626917, 2022). "The aim of this study was to examine ceruloplasmin in patients with heart failure related to cardiopulmonary exercise testing and assess the connection of ceruloplasmin with iron and hepatic status, and inflammatory and redox biomarkers." (PMID 34576235, 2021). "Accordingly, we propose that CP is important in the progression of heart failure due to its property of an acute phase protein, antioxidant function and regulation of nitric oxide homeostasis." (PMID 24206753, 2013). "Similarly, in African studies, elevated ceruloplasmin levels were observed in conditions like cardiomyopathy, heart failure, and venous thromboembolism." (PMID 39574108, 2024). "Large clinical studies proved CP association with incident heart failure, mortality, and cardiovascular diseases in the Atherosclerosis Risk in Communities (ARIC) population 32 as well as a direct relationship between ceruloplasmin elevated levels and incidence of coronary heart disease." (PMID 37324184, 2023). "Finally, also previously proposed diagnostic markers of heart failure, including carbonic anhydrase 1 (CA1) and ceruloplasmin (CP), were among the more abundant proteins in failing hearts." (PMID 33670142, 2021). "In nonischemic cardiomyopathy patients, the ceruloplasmin value was an independent biomarker associated with the extent of heart failure." (PMID 23781119, 2013). "We showed that both PBMCs and failing myocardium could be a major source of ceruloplasmin that is subsequently found in the serum of patients with heart failure." (PMID 24206753, 2013). "The results showed that only CP levels (χ2 = 4.489, odds ratio (OR) = 1.010, 95% confidence interval (CI): 1.001–1.019, P = 0.034) and age (P = 0.046) were correlated with the extent of heart failure." (PMID 23781119, 2013). "In nonischemic cardiomyopathy patients, the CP value was an independent biomarker associated with the extent of heart failure." (PMID 23781119, 2013). "Our study aimed to evaluate the predictive value of serum ceruloplasmin in patients with ischemic and nonischemic cardiomyopathies, and assess the association between CP levels and the extent of heart failure, CP levels and other parameters in both ischemic and nonischemic cardiomyopathy patients." (PMID 23781119, 2013).
liver disease (15 papers, 2013 to 2026). "The c.2333G>T(p.R778L) variant in the ATP7B gene is the most prevalent pathogenic variant among Asian patients with WD, and those patients carrying this variant predominantly present with early liver disease and low serum ceruloplasmin." (PMID 40104154, 2025). "WD typically manifests with isolated liver disease, and diagnosis involves evaluating Kayser-Fleischer rings, serum CP levels, urine copper levels, liver biopsy, and genetic testing." (PMID 39440108, 2024). "On univariate analysis, aetiology of liver disease (non‐viral vs viral), older age, performance status (CCI and ECOG) and worse hepatic function (CP, MELD, ALBI) were associated with inferior OS." (PMID 38400681, 2024). "Patients with other liver disease and nervous and mental diseases also had significantly lower mean serum CP levels." (PMID 29324775, 2018). "Measurement of serum CP has been used to diagnose WD, a liver disease in which serum CP levels are decreased in up to 95% of symptomatic patients." (PMID 24282481, 2013). "Both siblings had visible ocular Kayser-Fleischer rings, low serum ceruloplasmin level and increased urinary copper content, ultrasound-evidenced cirrhotic liver disease, and axial T2-weighted MRI hyperintensities in basal ganglia, thalamus, and brainstem (midbrain and pons)." (PMID 32774387, 2020). "Rather than to prove the broader pathophysiological role of CP in serious liver disease, we hypothesized that CP can be applied effectively as a biomarker to help improve the non-invasive diagnosis of liver fibrosis in CHB patients and predict progression to cirrhosis." (PMID 24282481, 2013).